MAP3K14 (mitogen-activated protein kinase kinase kinase 14)
Description:
Lymphotoxin beta-activated kinase which seems to be exclusively involved in the activation of NF-kappa-B and its transcriptional activity. Phosphorylates CHUK/IKKA, thereby promoting proteolytic processing of NFKB2/P100, which leads to NF-kappa-B activation via the non-canonical pathway. Has an essential role in the non-canonical NF-kappa-B signaling that regulates genes encoding molecules involved in B-cell survival, lymphoid organogenesis, and immune response. Could act in a receptor-selective manner.
Synonyms: HsNIK; NIK; FTDCR1B; HS; IMD112
Tractability: Small molecule: a structure with a bound ligand is known; a high-quality ligand is known; it belongs to a druggable protein family. PROTAC: UniProt records ubiquitination sites on it; ubiquitination databases record sites on it; a small molecule that binds it is known.
Target class: Enzyme; STE protein kinase unique family; Protein Kinase; STE protein kinase group; Kinase
Chemical probes: NIK-SMI1 (high quality)
Gene: Protein-coding gene on chromosome 17 (45,263,119 to 45,317,112, reverse strand). Ensembl gene ENSG00000006062.
Subcellular location: Cytoplasm
Subcellular location (Human Protein Atlas): Cytosol; Vesicles; Nucleoli fibrillar center; Nucleoplasm
Pathways (Reactome):
Immune System: CD28 dependent PI3K/Akt signaling; Dectin-1 mediated noncanonical NF-kB signaling; NIK-->noncanonical NF-kB signaling; TNF receptor superfamily (TNFSF) members mediating non-canonical NF-kB pathway; TNFR2 non-canonical NF-kB pathway
Gene Ontology:
Molecular function: protein binding; protein kinase activity; protein serine/threonine kinase activity; ATP binding; MAP kinase kinase kinase activity; protein serine kinase activity
Biological process: cellular response to mechanical stimulus; defense response to virus; non-canonical NF-kappaB signal transduction; immune response; MAPK cascade
Cellular component: cytosol; cytoplasm
Genetic constraint (gnomAD): Loss-of-function variants: 16 observed, 92.28 expected, observed/expected ratio (o/e) 0.17, 90% interval 0.12 to 0.26. The upper end of that interval is the gene's LOEUF score, 0.26, which puts it in group 1 of 6, group 1 being the genes least tolerant of losing a copy. Missense variants: 782 observed, 1,212.4 expected, observed/expected ratio (o/e) 0.64, 90% interval 0.61 to 0.68. Synonymous variants: 459 observed, 494.6 expected, observed/expected ratio (o/e) 0.93, 90% interval 0.86 to 1.
Gene-disease validity (ClinGen):
ClinGen rates the evidence that MAP3K14 causes each of these diseases.
NIK deficiency (autosomal recessive): Moderate. A immunodeficiency disorder caused by loss of function mutation in NIK (MAP3K14).
Homologues: Orthologues: chimpanzee MAP3K14 (99% identical), macaque MAP3K14 (98% identical), pig MAP3K14 (90% identical), dog MAP3K14 (90% identical), rat Map3k14 (85% identical), mouse Map3k14 (84% identical), guinea pig MAP3K14 (81% identical), tropical clawed frog map3k14 (39% identical), zebrafish map3k14a (32% identical), zebrafish map3k14b (24% identical). Paralogues in human: MAP4K4 (15% identical), TNIK (15% identical), MINK1 (14% identical), STK10 (13% identical), MAP4K2 (13% identical), MAP4K1 (13% identical), NRK (13% identical), SLK (13% identical), MAP4K3 (13% identical), MAP4K5 (12% identical), TAOK1 (12% identical), MAP3K1 (12% identical), and 23 more.
Diseases named in the same sentence as MAP3K14 in open-access papers:
MAP3K14 is named in the same sentence as 69 diseases in open-access papers, as found by Europe PMC text mining. Sharing a sentence is not in itself a finding about the gene and the disease. The quoted sentences say what the papers report.
glioma (4 papers, 2015 to 2025). A benign or malignant brain and spinal cord tumor that arises from glial cells (astrocytes, oligodendrocytes, ependymal cells). "The network topology analysis performed in this study revealed a set of central nodes associated to glioma malignancy, such as Map3k14, Mapk1, Actn4, Hspa5, Atf2, Rac1,E2f1, Shc1, Pik3ca, Akt1, Vim and Egr1." (PMID 26582089, 2015). "Notably, despite the established role of TRAF3 as an inhibitor of the NF-κB pathway in glioma, restoration of the alternative NF-κB pathway by expression of MAP3K14 did not rescue the effect of TRAF3 overexpression on the oxidation capacity of GBM cells." (PMID 39932808, 2025). "Specifically, NF-κB-inducing kinase (NIK; encoded by MAP3K14), which is an essential upstream kinase for noncanonical NF-κB activation, increases matrix metalloproteinase 1 (MT1-MMP) activity to promote invadopodia formation during glioma invasion." (PMID 36945490, 2023).
melanoma (4 papers, 2012 to 2021). A malignant, usually aggressive tumor composed of atypical, neoplastic melanocytes. "miR-31 targets include oncogenic kinases such as SRC, MET, NIK (MAP3K14) and the melanoma specific oncogene RAB27a." (PMID 22948084, 2012).
psoriasis (4 papers, 2015 to 2025). An autoimmune condition characterized by red, well-delineated plaques with silvery scales that are usually on the extensor surfaces and scalp. "MAP3K14 is an NF-κB-inducing kinase and NF-κB has been long known to have a key role in inflammatory processes in psoriasis." (PMID 39337694, 2024). "In order to assess the functional impact of NIK-lesioned γδ T cells, we treated Map3k14-/- animals with Imiquimod, a well established system for the induction of psoriasis-like skin inflammation in mice." (PMID 26637788, 2015). "Similarly, miR-21-3p overexpression promotes Th17 differentiation and activates the IL-23/IL-17 axis through MAP3K14, exacerbating inflammation in a psoriasis model." (PMID 40746566, 2025). "Contrary to our hypothesis, deficiency in Map3k14 or Nfkb2 did not prevent the psoriasis-like skin disease in Traf2EKO mice." (PMID 26701909, 2015). "In particular, we suggest experimental validation of miRNAs hsa-miR-485-3p and hsa-miR-371a-3p and lncRNAs MAP3K14, ERAP1 and SPEN in skin lesions of psoriasis patients treated with biological drugs." (PMID 39337694, 2024).
breast carcinoma (3 papers, 2014 to 2023). "The highly pleiotropic MAP3K14 locus showed associations with diverse traits such as osteoarthritis, breast cancer, and hypothyroidism." (PMID 36598836, 2023).
myeloma (3 papers, 2012 to 2019). "The most common translocations unique to IgL were MAP3K14 and 3q26.2 (a region not clearly associated with expression of a single gene), which only accounted for 7.4 and 4.9% of t(IgL) myeloma, respectively." (PMID 31015454, 2019). "Several predictions and experimental approaches have defined a novel miR-31 target gene, MAP3K14 (also called NIK), which is a persistent NF-κB activator in various malignancies, including B cell lymphoma, multiple myeloma, breast cancer, pancreatic cancer, and ATL." (PMID 23060864, 2012).
osteosarcoma (3 papers, 2019 to 2023). A usually aggressive malignant bone-forming mesenchymal neoplasm, predominantly affecting adolescents and young adults. "Furthermore, although prior studies have shown that E2F regulation of cIAPs and E2F1 directly promotes MAP3K14 gene expression in osteosarcoma cells, we report for the first time that the E2F transcription factors E2F4 and E2F5 play a role in regulating NIK transcription and expression." (PMID 36945490, 2023). "In osteosarcoma cells, CDK12 could also play a role in transcriptional regulation of the MAP3K14 and NFKB2 mRNA expression, participating in activation of noncanonical NF-κB pathway." (PMID 31523177, 2019).
adenocarcinoma of the lung (2 papers, 2018 to 2021). "MAP3K14 and MAP2K1 may serve as potential therapeutic targets in the treatment of lung adenocarcinoma in the future." (PMID 33442956, 2021).
allergic asthma (2 papers, 2019 to 2022). A asthma with a basis in a pathological type I hypersensitivity reaction. "Namely, for environment IgE sensitization (METTL1), for allergic asthma (NTRK1), and several for FeNO (MAP3K14, NTRK1, FBXL7, PCSK6, SLC9A3, CDH26, CAPN14, and MAP3K14)." (PMID 31300640, 2019).
COVID-19 (2 papers, 2022 to 2025). A disease caused by infection with severe acute respiratory syndrome coronavirus 2. "The fourth set of modules involved ribosomal proteins and inflammasome function (top genes by membership included NLRP1, MAP3K14, and FOXP1) and was negatively correlated with COVID-19 severity in monocytes." (PMID 35216673, 2022).
hepatocellular carcinoma (2 papers, 2022 to 2024). A malignant tumor that arises from hepatocytes. "Genetic alterations and CNVs are common sources of dysregulated gene expression 48, we further explored the relationship between the mutation status of MAP3K14 in hepatocellular carcinoma samples and prognosis." (PMID 38577603, 2024). "However, further elucidation is still needed regarding the association between MAP3K14 expression and hepatocellular carcinoma (HCC), as well as its role in HCC." (PMID 38577603, 2024). "Therefore, this study aims to analyze the expression level of MAP3K14 and its prognostic significance in hepatocellular carcinoma using data mining from multiple databases." (PMID 38577603, 2024). "Down-regulation of the expression of MAP3K14 may improve the sensitivity of targeted drug therapy for hepatocellular carcinoma and improve the prognosis of patients." (PMID 38577603, 2024). "MAP3K14 also plays a significant role in the development of non-alcoholic steatohepatitis (NASH)-related hepatocellular carcinoma and its connection to tumor stem cells." (PMID 38577603, 2024).
Hodgkins lymphoma (2 papers, 2015 to 2022). A heterogeneous group of malignant lymphoid neoplasms of B-cell origin characterized histologically by the presence of Hodgkin and Reed-Sternberg (HRS) cells in the vast majority of cases. "TRAF3 deletions and MAP3K14 gains are also frequently observed in Hodgkin lymphoma." (PMID 35911754, 2022).
Insulin resistance (2 papers, 2021 to 2023). Increased resistance towards insulin, that is, diminished effectiveness of insulin in reducing blood glucose levels. "Specific slow type myosin heavy chain components were associated with AL (MYH7) and BI (MYH3) pigs, while an overexpression of MAP3K14 in AL may be associated with their lower loin proportion, induced insulin resistance, and increased inflammatory response via NFkB activation." (PMID 34065673, 2021). "Accumulation of the non-canonical NF-κB-inducing kinase (NIK) in obesity drives insulin resistance in the liver and muscle and impairs insulin secretion in pancreatic beta cells, whereas deletion of Map3k14, which encodes NIK, renders mice hypoglycaemic and improves glucose tolerance." (PMID 37311878, 2023).
mantle cell lymphoma (2 papers, 2015 to 2024). Mantle cell lymphoma is a rare form of malignant non-Hodgkin lymphoma affecting B lymphocytes in the lymph nodes in a region called the ``mantle zone''. "Both have been reported as mutated in human classical Hodgkin lymphoma as well as mantle cell lymphoma, where MAP3K14 was recently reported as a new therapeutic target." (PMID 26377837, 2015). "Because mutations in other NF-κB pathway genes, including BIRC3, TRAF2, TRAF3, MAP3K14 and CARD11, have been associated with ibrutinib resistance in mantle cell lymphoma, we next investigated whether mutations in NFKBIE could also affect the response to ibrutinib treatment." (PMID 38486128, 2024).
prostate carcinoma (2 papers, 2008 to 2016). A carcinoma that arises from epithelial cells of the prostate gland. "Thus, increased MAP3K14 transcription by ErbB380kDa is strongly to be involved in bone resorption during prostate cancer progression, through constitutive activation of the non-canonical NF-ĸB signalling pathway." (PMID 27191720, 2016).
renal carcinoma (2 papers, 2022 to 2024). A carcinoma arising from the epithelium of the renal parenchyma or the renal pelvis. "The lncRNA H19 regulates GLIOMA angiogenesis, while MAP3K14 is one of the well-recognized biomarkers in the prognosis of renal cancer, which is reminiscent of the pancreatic metastasis from renal cell carcinoma." (PMID 38741200, 2024). "Interestingly, FYN, LRSAM1, IL20RB, CXCL11, S100A1, and MAP3K14 are also well-recognized biomarkers in the prognosis of renal cancer, which is reminiscent of the pancreatic metastasis from renal cell carcinoma in some earlier studies." (PMID 36428747, 2022).
viral infection (2 papers, 2017 to 2020). "We found that Map3k14 is a key mediator of immune surveillance during viral infection, as it promotes the immune activation, which is dependent on viral replication in the spleen." (PMID 32033109, 2020). "The MAP3K14 PID is associated with several microbial infections, including bacterial and viral infections." (PMID 28448599, 2017).
acute myocardial infarction (1 paper, 2025). Necrosis of the myocardium, as a result of interruption of the blood supply to the area. "In acute myocardial infarction mouse models, five genes (Ptpn6, Csf1r, Col6a1, Cyba, and Map3k14) have been implicated in the acute myocardial infarction pathway by regulating DNA methylation, suggesting their potential as early methylated biomarkers for clinical diagnosis." (PMID 40428388, 2025).
combined immunodeficiency (1 paper, 2017). A broad classification of inherited disorders presenting at birth that affect both the cell-mediated and humoral aspects of the immune response. "This study describes the use of exome sequencing to identify a homozygous recessive variant in MAP3K14, NIKVal345Met, in a patient with combined immunodeficiency, disseminated BCG-osis, and paradoxically elevated lymphocytes." (PMID 29230214, 2017).
diabetes (1 paper, 2015). "Up-regulation of MAP3K14 had been linked to the persistent inflammatory response in diabetes." (PMID 26430762, 2015).
Immunodeficiency (1 paper, 2021). Failure of the immune system to protect the body adequately from infection, due to the absence or insufficiency of some component process or substance. "Mice and patients with germline mutations in Map3k14 (encoding NIK) or Relb exhibit spontaneous T-cell activation and profound immunodeficiency, though this may rely on T-cell-extrinsic mechanisms." (PMID 34608221, 2021).
liver cancer (1 paper, 2024). An epithelial or non-epithelial malignant neoplasm that arises from the liver. "Multivariate Cox regression analysis showed that the Pathologic stage (p < 0.001) and MAP3K14 expression levels (p < 0.05) is an independent prognostic factor affecting the survival of patients with liver cancer." (PMID 38577603, 2024). "According to the cytoplasmic staining score criteria, the protein level of MAP3K14 was significantly higher in liver cancer tissues compared to the corresponding non-cancerous tissues, which is consistent with the predicted results from public databases." (PMID 38577603, 2024). "The results showed that MAP3K14 protein levels were significantly higher in liver cancer tissues compared to corresponding non-cancerous tissues, and patients with higher MAP3K14 expression had shorter overall survival, consistent with the analysis of public databases." (PMID 38577603, 2024).
lung carcinoma (1 paper, 2014). "MAP3K3 and MAP3K14 are in the MAPK/ERK pathway which is a target of many novel therapeutic agents, and SRC is a well known oncogene and a candidate target in lung cancer." (PMID 25170874, 2014).
lung squamous cell carcinoma (1 paper, 2023). "MAP3K14 has been found to be differentially expressed and hypermethylated in lung squamous cell carcinoma, where it regulates the NF-κB activity pathway and participates in NF-κB-inducing signaling through receptors of the tumor-necrosis/nerve-growth factor (TNF/NGF) family." (PMID 37628872, 2023).
lymphopenia (1 paper, 2020). Reduction in the number of lymphocytes. "More importantly, the functional lack of the Map3k14 resulted in general B cell lymphopenia, with no MZ B cells being detected; however, the follicular B cells were mainly unaffected." (PMID 32033109, 2020).
multiple sclerosis (1 paper, 2017). A progressive autoimmune disorder affecting the central nervous system resulting in demyelination. "In human, the MAP3K14 gene is associated with multiple sclerosis, which involves motor and sensory dysfunction." (PMID 28813538, 2017).
osteopetrosis (1 paper, 2023). Osteopetrosis, also known as marble bone disease, is a descriptive term that refers to a group of rare, heritable disorders of the skeleton characterized by increased bone density on radiographs. "We previously showed that lymphoid hypoplasia (aly/aly) mice with a natural loss-of-function mutation in the map3k14 gene, which encodes a kinase essential for p100 to p52 processing in the NF-κB alternative pathway, exhibit osteopetrosis in association with decreased osteoclast numbers." (PMID 37143646, 2023).
pancreatic adenocarcinoma (1 paper, 2011). "The relative abundance of two sense (DAPK1, MAP3K14) and one antisense-oriented (PPP3CB) intronic transcripts in samples of primary pancreatic adenocarcinoma and pancreatic metastases was independently accessed by qRT-PCR, confirming the results measured in the microarray hybridizations." (PMID 22078386, 2011).
preeclampsia (1 paper, 2025). Preeclampsia is a hypertensive disorder of pregnancy that is characterized by new-onset hypertension with proteinuria presenting after 20 weeks of gestation, and depending on mild or severe forms may initially present with severe headache, visual disturbances, and hyperreflexia. "Ultimately, functional studies in relevant cell and animal models are essential to confirm the causal impact of ATG16L1, PMVK, MAP3K14, NSUN2, and CDC25A on senescence phenotypes and preeclampsia pathogenesis." (PMID 41220585, 2025). "In conclusion, this multi-omics MR study, combined with preliminary experimental insights, pinpoints ATG16L1, PMVK, MAP3K14, NSUN2, and CDC25A as key candidate genes potentially mediating the link between cellular senescence pathways and odds of preeclampsia." (PMID 41220585, 2025). "Placental RT-PCR showed upregulated ATG16L1 and downregulated PMVK, MAP3K14, NSUN2, and CDC25A in preeclampsia." (PMID 41220585, 2025). "These preliminary experimental findings lend support to the potential relevance of ATG16L1, PMVK, MAP3K14, NSUN2, and CDC25A dysregulation in preeclampsia pathophysiology." (PMID 41220585, 2025). "Key genes (ATG16L1, PMVK, MAP3K14, NSUN2, CDC25A) link cellular senescence to preeclampsia, offering insights for mechanistic studies and therapeutic targeting." (PMID 41220585, 2025). "Our findings implicate several genes operating through diverse pathways—including ATG16L1, MAP3K14, PMVK, CDC25A, and NSUN2—as potential mediators linking senescence processes to odds of preeclampsia." (PMID 41220585, 2025). "Synthesizing these results, dysregulation across interconnected pathways—autophagy (ATG16L1), inflammation (MAP3K14), metabolism (PMVK), cell cycle (CDC25A), and RNA methylation (NSUN2)—appears to converge on promoting placental cellular senescence, contributing to preeclampsia pathophysiology." (PMID 41220585, 2025). "The results revealed that the expressions of ATG16L1, NSUN2 and PMVK were significantly downregulated in placental tissues from preeclampsia patients, whereas other key genes such as CDC25A and MAP3K14 did not vary significantly between groups." (PMID 41220585, 2025).
steatosis (1 paper, 2022). Increased lipid within the cytoplasm of cells. "This was accompanied by steatosis, increased Bax/Bcl-2 ratio, and overexpression of p-SAPK/JNK, Tgfβ1, Map3k14, and Col1a1 in the liver." (PMID 34663892, 2022).